CYP2D6 (cytochrome P450 family 2 subfamily D member 6 (gene/pseudogene))
Diseases named in the same sentence as CYP2D6 in open-access papers (continued):
Sharing a sentence is not in itself a finding about the gene and the disease.
nightmare (1 paper, 2019). A disturbing dream that occurs during rapid eye movement sleep and results in feelings of strong terror, fear, distress, or anxiety. "Contrastingly, CYP2D6 SSRI substrates are associated with ADRs related to nightmares, withdrawal syndrome, and de-realization of cognitive processes." (PMID 31616600, 2019).
oral cancer (1 paper, 2022). "This warrants a detailed investigation of the impact of CPC on the expressions of MDR1 and CYP2D6 in oral cancer cells." (PMID 35328402, 2022).
pancreatitis (1 paper, 2025). Inflammation of the pancreas. "Recent studies have suggested that genetic polymorphisms in drug-metabolizing enzymes, particularly cytochrome P450 isoforms such as CYP2D6 and CYP2C19, may significantly influence individual susceptibility to SSRI-induced adverse effects, including pancreatitis." (PMID 41561971, 2025).
parasitemia (1 paper, 2016). "Aiming to confirm this hypothesis, we retrospectively analyzed the CYP2D6 genotype of patients who were not re-infected but experienced recurrent parasitemia." (PMID 27467145, 2016).
parathyroid neoplasms (1 paper, 2025). "In a previous microarray study of gene expression in parathyroid neoplasms, significantly increased expression of CYP2D6 was also observed in PCs." (PMID 40525887, 2025).
personality disorder (1 paper, 2018). A diverse category of psychiatric disorders characterized by behavior that deviates markedly from the expectations of the individual's culture; this pattern of deviation is pervasive and inflexible and is stable over time. "Chronic use of Khat is associated with a variety of mental and personality disorders that require treatment, and CYP2D6 metabolizes several psychoactive drugs including psychotropic, anti-depressants and antipsychotics." (PMID 30143732, 2018).
porphyria (1 paper, 2024). Porphyria is a group of diseases in which substances called porphyrins build up, negatively affecting the skin or nervous system. "An investigative study conducted in Argentina focused on analyzing CYP2D6 polymorphisms in patients with porphyria, encompassing 121 participants, including 51 healthy volunteers, 50 porphyria patients, and 19 individuals with elevated iron levels." (PMID 39188285, 2024). "The results showed that the CYP2D6*3 and CYP2D6*4 alleles, particularly, were linked to the onset of porphyria." (PMID 39188285, 2024).
Priapism (1 paper, 2021). A painful and harmful medical condition in which the erect penis doesn't return to its flaccid state, despite the absence of both physical and psychological stimulation, within four hours. "Other factors that may increase the risk of priapism are prior history of priapism, use of multiple antipsychotics, and slow metabolism at CYP2D6, as many antipsychotics are metabolized by this enzyme." (PMID 34336343, 2021).
psoriasis (1 paper, 2021). An autoimmune condition characterized by red, well-delineated plaques with silvery scales that are usually on the extensor surfaces and scalp. "However, tildrakizumab, an anti‐IL‐23 mAb, had no clinically relevant effect on the exposure of any CYP probe substrates tested in the cocktail study (S‐warfarin, midazolam, dextromethorphan [CYP2D6], omeprazole, and caffeine) in patients with moderate to severe psoriasis." (PMID 33331142, 2021).
renal failure (1 paper, 2021). "Consequently, a risperidone-treated CYP2D6 IM patient with renal failure, where both risperidone and paliperidone are accumulated, obtains a substantially larger effect on the exposure of active moiety than predicted from the CYP2D6 genotype itself." (PMID 33967790, 2021).
Sinus bradycardia (1 paper, 2017). Bradycardia related to a mean resting sinus rate of less than 50 beats per minute. "These DDI predictions may explain the occurrence of severe sinus bradycardia after coadministration of bupropion and metoprolol and highlight the need for caution and dosage adjustment when combining bupropion with medications metabolized by CYP2D6." (PMID 29267251, 2017).
skin reaction (1 paper, 2012). "This could be partly explained by recent reports which showed that NVP was metabolically activated to quinone methidine, a toxic reactive metabolite, by CYP3A4, and, to a lesser extent, CYP2D6, CYP2C19, and CYP2A6, and that this reactive metabolite was responsible for NVP-induced skin reactions." (PMID 22957276, 2012).
somnolence (1 paper, 2020). "Further, tablet-based antidepressants that are significantly associated with somnolence and have no to minor CYP2D6 contribution are: desvenlafaxine and mirtazapine." (PMID 32201646, 2020).
supraventricular tachyarrhythmia (1 paper, 2020). "In a prospective study, 143 supraventricular tachyarrhythmia patients were concomitantly treated with flecainide and bepridil, a CYP2D6 inhibitor." (PMID 32906709, 2020).
type II diabetes (1 paper, 2021). "One study using a cocktail approach showed that CYP2B6, CYP2C19 and CYP3A activity decreased, CYP1A2 and CYP2C9 activity increased, and CYP2D6 and CYP2E1 activity was unaffected in type II diabetes (T2D)." (PMID 34867341, 2021).
ulcerative colitis (1 paper, 2021). An inflammatory bowel disease involving the mucosal surface of the large intestine and rectum. "We also note that according to Sen and Stark (2019), CYP2D6*4 polymorphisms may be risk factors for ulcerative colitis." (PMID 33763108, 2021).
Urinary incontinence (1 paper, 2023). Loss of the ability to control the urinary bladder leading to involuntary urination. "A total of 71 participants (30 ± 10 years old, 82% male, 45% CYP2D6 NM phenotype (32 participants)) with a median of 3 (IQR 2–4) comorbidities per person, mainly urinary incontinence (32%) and constipation (22%), were included." (PMID 37513866, 2023).
urinary tract tumours (1 paper, 2022). "Notably, in the past, CYP2D6 was considered to have a major role in OTA toxicity based on the apparent increased risk of extensive CYP2D6 metabolisers to develop OTA-related diseases (e.g., urinary tract tumours and Balkan endemic nephropathy (BEN))." (PMID 35324704, 2022).
Xeroderma pigmentosum complementation group C (1 paper, 2022). "Genes also involved in NMSCs pathogenesis are melanocortin-1 receptor (MC1R), xeroderma pigmentosum complementation group C (XPC), cytochrome P450 2D6 (CYP2D6), cyclin dependent kinase inhibitor 2A (CDKN2A), glutathione S-transferase theta 1 gene (GSTT1), and telomerase." (PMID 36291078, 2022).
cancer (68 papers, 1994 to 2026). A tumor composed of atypical neoplastic, often pleomorphic cells that invade other tissues. "In contrast, the anti-cancer drug tamoxifen had 10-fold fewer prescriptions; thus, screening CYP2D6 for high-frequency alleles (*29, *17, *10, *41) would result in tangible benefits for patient’s clinical outcomes." (PMID 38276236, 2024). "Talazoparib has also been reported to undergo slow metabolism by the liver, aligning with our discovery that cancer cells with lower CYP2D6 activity exhibit heightened susceptibility to talazoparib treatment." (PMID 39368455, 2024). "TNBG-5602, as a potent inhibitor of CYP2D6, is likely to cause drug–drug interactions when used in a combination method for the treatment of cancer." (PMID 35458793, 2022). "The relationship between CYP2D6 allelic variants and cancer incidence is still debatable due to conflicting reports." (PMID 34597305, 2021). "In other cancers, CYP2D6 polymorphisms were demonstrated to be associated with prostate, bladder and renal cancers." (PMID 33192522, 2020). "The number of CYP2D6 polymorphisms is over seventy-five, and the association between CYP2D6 polymorphisms and cancer risk has been studied for many years." (PMID 33192522, 2020). "To date, there have been studies that have shown that genetic polymorphisms of CYP2D6 increase the susceptibility to numerous cancers." (PMID 31264381, 2019). "The role of the CYP2D6 gene as a risk factor for tobacco-related cancers has been extensively studied since early reports suggested an association between the high-metabolizing CYP2D6 phenotype and HNC risk in smokers." (PMID 24151610, 2013). "Epidemiological evidence from retrospective studies indicates an association between CYP2D6 variations and altered tamoxifen response in a range of therapeutic settings such as metastatic breast cancer, cancer prevention, and adjuvant therapy." (PMID 21187922, 2010). "Additionally, mutant CYP2D6 alleles have been implicated as a predictor of susceptibility for diseases such as cancer and for neurological disorders." (PMID 29182577, 2017). "In future studies, the impact of CYP2D6 genetic variants on the plasma concentrations of tramadol and its desmethylates and clinical effects should be evaluated in patients with cancer pain or non-cancer pain." (PMID 27729987, 2016). "Additionally, variations in the CYP2D6 gene have been studied as a risk factor for a number of diseases: Parkinson’s disease, schizophrenia and other psychiatric diseases, Alzheimer’s disease, and several forms of cancer." (PMID 35330374, 2022). "Some examples of anti-cancer drugs metabolized by CYP enzymes include tamoxifen by CYP2D6, docetaxel and cyclophosphamide by CYP3A4/5, and paclitaxel by CYP2C8." (PMID 41009411, 2025). "The dual relevance of CYP2D6 in ADHD medication efficacy and cancer risk reflects complex interactions between genetic factors and environmental exposures but does not imply a single, common mechanism underlying the development of ADHD." (PMID 40182194, 2025). "There is no current recommendation for change in oxycodone dose or prescribing for the different CYP2D6 phenotypes for cancer-related pain." (PMID 39628313, 2024). "The VEN case in the present study (case #1) displayed that her genotyping of CYP2D6 and 2C19 were gIMs and became pPMs due to disease-induced phenoconversion (cancer)." (PMID 38668482, 2024). "This motivates future clinical studies where the use of CYP2D6 activity-dependent anti-cancer drugs is guided by constitutional and tumour CYP2D6 genotype." (PMID 39368455, 2024). "Our results identified many novel variants located in essential genes to cancer (DPYD, TYMS, MTHFT, and GSTT1), infectious diseases (IFNL4), and psychiatric treatments (CYP2D6)." (PMID 35743738, 2022). "CYP2D6 metabolizes a wide range of drugs: antiarrhythmics, tricyclic and second-generation antidepressants, β-blockers, anti-cancer drugs, several opioid analgesics including codeine and tramadol, and many more." (PMID 35330374, 2022).
cancer (continued). "Non-cancer therapy consisted of ondansetron (CYP2D6—CPIC Level A) for nausea, as well as morphine (OPRM1, COMT—CPIC level C) and tramadol (CYP2D6—CPIC Level A, FDA Tier 1; OPRM1, COMT—CPIC level C) for pain management." (PMID 33799547, 2021). "A recent study in cancer patients shows that CYP2D6 genotype impacts on plasma concentrations of tramadol and its demethylated metabolites, as well as drug tolerability." (PMID 32708424, 2020). "In summary, CYP2D6 isoenzyme is involved in opioid PK and is able to influence analgesic effect and adverse events in patients with cancer pain." (PMID 32708424, 2020). "CYP2D6 metabolizes many clinically important drugs, including antidepressants, neuroleptics, beta-blockers, anti-arrhythmics, and anti-cancer agents." (PMID 23207012, 2012). "For example, cancer drugs with actionable drug-gene pairs (e.g., CYP2D6-tamoxifen, DPYD-fluoroucil, DPYD-tegafur, UGT1A1-irinotecan, DPYD-capecitabine) could be considered." (PMID 40894378, 2025). "Polymorphisms in the CYP2D6 gene impact the metabolism and activation of tamoxifen, consequently influencing its therapeutic efficacy and side effect profile during the treatment of BRCA-related cancers." (PMID 41278297, 2025). "rs35742686 in the CYP2D6 gene (CYP2D6*3), which can have a three times higher frequency in San populations compared with Europeans and East Asians, interferes with converting the anti-cancer drug tamoxifen into its anti-estrogenic metabolites." (PMID 41465076, 2025). "Among cancer patients prescribed oxycodone, a cross-sectional multicenter study revealed no statistically significant variance in serum oxymorphone concentrations between CYP2D6 ultrarapid metabolizers and normal metabolizers." (PMID 38793067, 2024). "Our study, like these other clinical studies conducted, suggests that there is no clinically significant difference in pain and adverse effect outcomes in a cancer population based on whether they are CYP2D6 NMs, or IM/PMs." (PMID 39628313, 2024). "In addition, CYP2D6, CYP3A4, CYP2B6, and CYP2C19 are implicated in anti-cancer metabolism, influencing their efficacy." (PMID 39062040, 2024). "CYP2D6 is vital in converting anti-cancer drug tamoxifen to its active form." (PMID 38789983, 2024). "Among the FDA-approved biomarkers for anti-cancer drugs, there are: cytochrome P450 2D6 (CYP2D6) for tamoxifen; rucaparib and dihydropyrimidine dehydrogenase (DPYD/DPD) for fluorouracil and capecitabine; and thiopurine S-methyltransferase (TPMT) for cisplatin, mercaptopurine, and thioguanine." (PMID 35205356, 2022). "Testing CYP2D6 in the clinical setting provided interesting data; although less of them come from the specific scenario of cancer pain management, they suggest that CYP family testing may help better opioid prescribing." (PMID 32708424, 2020). "SSRIs may also affect cancer outcomes by interfering with tamoxifen metabolism through inhibition of the CYP2D6 enzyme." (PMID 29351761, 2018). "Although others have suggested that SSRIs could lead to poorer cancer outcomes through inhibition of the CYP2D6 enzyme among tamoxifen users, this was only partially supported by our study." (PMID 29351761, 2018). "Cigarette smoking is an independent risk factor for cervical neoplasia, suggesting that polymorphism at detoxicating enzyme loci such as cytochrome P450 CYP2D6 and glutathione S-transferase GSTM1 may determine susceptibility to these cancers." (PMID 7917923, 1994). "CYP2D6 is the only gene that has pharmacogenomic prescribing guidance for any opioid; however, this is currently limited to the weak opioids codeine and tramadol, limiting its application in cancer pain prescribing where more potent opioids are usually required." (PMID 39628313, 2024).
cancer (continued). "Tamoxifen has been in clinical use for the treatment of cancer since the 1970s but the relatively recent discovery of endoxifen, coupled with an increased understanding of the phenotypic variability of CYP2D6, has suggested opportunities for further optimization of therapy." (PMID 27756789, 2017). "This review highlights the impact of key genes, such as CYP2D6, DPYD, and UGT1A1, which influence the metabolism of essential cancer drugs like tamoxifen, fluoropyrimidines, and irinotecan." (PMID 40149251, 2025). "CYP2D6 is perhaps the most extensively studied CYP enzyme in the context of pharmacogenomics and cancer." (PMID 40149251, 2025). "TIMER database was used for pan‐cancer analysis of different pain genes (Nav1, EHMT2, SP1, SLC6A4, COMT, OPRM1, OPRD1, CYP2D6, and CYP3A4)." (PMID 38352696, 2024). "For example, we identified 41 patients in two cancer types receiving tamoxifen where the genes UGT1A10, UGT2B15, or CYP2D6 were highly expressed." (PMID 29783934, 2018). "In cancer cells, PGRMC1 facilitates the degradation of the chemotherapeutic agent doxorubicin by activating CYP2D6 or CYP3A4, leading to a reduction of the anti-cancer effect of doxorubicin." (PMID 30087538, 2018). "In general, it is believed that CYP2D6 genotype does not affect cancer pain patients treated with oxycodone." (PMID 37990344, 2023). "In this field, numerous studies conducted on different populations and ethnic groups have indicated the absence of a major impact of the CYP2D6, CYP2C19 and CYP2E1 genes in cancer risk." (PMID 18423013, 2008). "Our study aimed to examine whether the predominant pathway for oxycodone metabolism – CYP2D6 and CYP3A4 – metaboliser status affect oxycodone dose, pain scores, and adverse effects in an Australian patient population with pain from advanced cancer, a population which commonly requires oxycodone." (PMID 39628313, 2024). "Quantitatively, CYP2D6 represents approximatively 1% to 4% of all hepatic CYP450 enzymes and metabolizes approximately 25% of medicines authorized for prescription by international agencies (e.g., anti-cancer agents, anti-depressants, anti-psychotics, and opioids)." (PMID 38138882, 2023). "The CYP2D6*10 SNP is relevant to tramadol pharmacokinetics and opioid dose requirement, while SNPs within UGT2B7 (rs7439366), ABAT (rs1641025), and P2RX7 (rs1718125) have demonstrated some level of potential clinical relevance to cancer pain pharmacogenomics in Asian patients." (PMID 36422103, 2022). "Cancer research studies are not in agreement with the role of CYP2D6 in the development of cancer." (PMID 35330374, 2022).